BRAF (B-Raf proto-oncogene, serine/threonine kinase)
Diseases named in the same sentence as BRAF in open-access papers (continued):
Sharing a sentence is not in itself a finding about the gene and the disease.
metastatic melanoma (continued). "The BRAF inhibitors vemurafenib and dabrafenib were first approved as single agents by the Food and Drug Administration (FDA) for the treatment of BRAF-mutated unresectable or metastatic melanoma." (PMID 29137342, 2017). "Similar results could be obtained when another BRAF inhibitor, dabrafenib, was used in patients with metastatic melanoma and further BRAF inhibitors (e.g., encorafenib) are now in clinical trials." (PMID 28350340, 2017). "For example, vemurafenib (Zelboraf®, F. Hoffmann-La Roche Ltd, Basel, Switzerland), a potent inhibitor of BRAF, significantly improved OS and progression-free survival (PFS), compared with dacarbazine, in patients with previously untreated metastatic melanoma harboring a BRAFV600E mutation." (PMID 29176861, 2017). "Consequently, BRAFV600-mutant metastatic melanoma patients treated with combination BRAF and MEK inhibitors, rarely develop resistance due to alternate BRAF splicing." (PMID 28503307, 2017). "The tolerability profiles in this phase I study have been seen in subsequent placebo-controlled, phase II trials of selumetinib plus dacarbazine in patients with treatment-naïve BRAF-mutant metastatic melanoma and selumetinib plus docetaxel in pretreated patients with KRAS-mutant advanced NSCLC." (PMID 28264648, 2017). "A multivariate analysis of BRAF mutations in patients with metastatic melanoma (N = 109) did not identify BRAF mutation as an independent prognostic indicator of overall survival (OS)." (PMID 29176861, 2017). "Dabrafenib (GSK2118436), registered as Tafinlar®, is an inhibitor of BRAF V600E approved for treatment of non-resectable stage III or stage IV metastatic melanoma carrying the mutation." (PMID 28429064, 2017). "MEK and BRAF inhibitors hence presented a new treatment method for metastatic melanoma." (PMID 28954413, 2017). "In light of this, an indirect treatment comparison was performed between two BRAF/MEK inhibitor combination therapies for metastatic melanoma, dabrafenib plus trametinib and vemurafenib plus cobimetinib, in order to understand the relative efficacy and toxicity profiles of these therapies." (PMID 28052762, 2017). "Several clinical trials have convincingly shown that immune checkpoint inhibitors increase the overall survival of metastatic melanoma patients with or without BRAF/NRAS mutations." (PMID 28231855, 2017). "BRAF inhibitors have a crucial role in patients with inoperable metastatic melanoma." (PMID 27042173, 2016). "Early detection of progression is important in metastatic melanoma, because of the aggressive course of the disease as exemplified by the observation that the central nervous system is a frequent site (30 %) of first progression under BRAF inhibitor therapy." (PMID 27095081, 2016). "BRAF genotyping is important for the treatment of patients with metastatic melanoma." (PMID 27111917, 2016). "Understanding how this occurred could provide greater insight into how vemurafenib exerts its effect in BRAF-mutant metastatic melanoma." (PMID 26857260, 2016). "As BRAF inhibition is potent against metastatic melanoma, but allows for recurrence in time, we ultimately set out to determine to what extent this peptide could be complementary to the clinically frequently prescribed BRAFV600E-inhibitor PLX4032, Vemurafenib." (PMID 26279295, 2016). "The first phase III trial with nivolumab as a first-line therapy was conducted in 418 treatment-free patients with metastatic melanoma lacking a mutation in BRAF." (PMID 26899259, 2016). "Thus this study represents the first comprehensive analysis of these genes in metastatic melanoma patients in relation to the treatment with BRAF inhibitors." (PMID 26863566, 2016). "Therefore, rapid screening for BRAF status in patients with unresectable or metastatic melanoma has recently become integral to treatment decisions and essential for optimal patient care." (PMID 27863476, 2016).
metastatic melanoma (continued). "Several other clinical trials demonstrating lack of sufficient clinical activity of bortezomib in patients with metastatic melanoma have also failed to take BRAF mutation status into account (NCT00288041, NCT00580320, NCT01462773, and NCT01078961)." (PMID 27783987, 2016). "BRAF-targeted therapy has already been shown clinical efficacy for metastatic melanoma." (PMID 27529619, 2016). "In addition, nivolumab + ipilimumab combination therapy has recently been granted an accelerated approval as a treatment for BRAF V600 wild-type unresectable or metastatic melanoma in the US based on findings from the CheckMate-069." (PMID 27069772, 2015). "BRAF inhibitors are now the first-line treatment for patients with unresectable or metastatic melanoma which test is positive for BRAFV600, in accordance with the recommendations of the health authorities such as the National Comprehensive Cancer Network and European guidelines." (PMID 26204954, 2015). "Pembrolizumab was the first anti-PD-1 antibody to be approved by the US Food and Drug Administration for the treatment of patients with unresectable or metastatic melanoma with disease progression following ipilimumab, and if BRAFV600 mutation positive, a BRAF inhibitor." (PMID 26288737, 2015). "However, its clinical benefit in patients whose metastatic melanoma progressed on a prior BRAF inhibitor treatment is only modest at best." (PMID 25962795, 2015). "Therapeutic agents that selectively target BRAF (e.g., vemurafenib, dabrafenib) or its downstream substrate MEK (e.g., trametinib) can improve overall survival in BRAF-mutant metastatic melanoma patients; however, their use as monotherapy is limited by intrinsic and acquired resistance." (PMID 26137449, 2015). "For the moment, BRAF inhibitors are limited to treatment of metastatic melanomas only." (PMID 25318602, 2015). "Oncogenic mutations in the BRAF gene, encoding a serine threonine kinase that is an essential part of the RAS–RAF–MEK–ERK signaling cascade have been found in approximately 50–70% of metastatic melanoma." (PMID 26139106, 2015). "The development of pembrolizumab from the first-in-humans study to FDA approval for the treatment of patients with unresectable or metastatic melanoma with disease progression following ipilimumab, and if BRAFV600 mutation positive, a BRAF inhibitor, has occurred in a record 3.6 years." (PMID 26288737, 2015). "The identification of oncogenic mutations in the BRAF gene have led to a revolution in the treatment of metastatic melanoma using targeted molecular therapies that affect the MAPK pathway either directly through BRAF inhibition or downstream through inhibition of MEK." (PMID 25785246, 2015). "The results suggest that ipilimumab is an effective and safe treatment for pretreated patients with metastatic melanoma regardless of BRAF and NRAS mutation status." (PMID 24885479, 2014). "In addition, the combination of the BRAF inhibitor dabrafenib and the MEK inhibitor trametinib improved progression-free survival in patients with BRAF V600E-mutated metastatic melanoma." (PMID 25422890, 2014). "We performed a cost-utility analysis to compare three strategies for patients with BRAF+ metastatic melanoma using a deterministic expected-value decision tree model to calculate the present value of lifetime costs and quality-adjusted life years (QALYs) for each strategy." (PMID 25198196, 2014). "Importantly, the effect of BRAF inhibition has also been studied in patients with metastatic melanoma." (PMID 25610709, 2014). "Outside of a clinical trial setting, ipilimumab is a feasible treatment option in patients with pretreated metastatic melanoma, regardless of BRAF and NRAS mutational status." (PMID 24885479, 2014). "Efforts to treat metastatic melanoma patients with broad spectrum multi-kinase inhibitors, as detailed below, would seem to be more broadly efficacious since they are independent of BRAF activating mutations, but in fact they are less so." (PMID 23515890, 2013).
metastatic melanoma (continued). "BRAF mutant protein was recently recognized as therapeutic target in metastatic melanoma." (PMID 23555633, 2013). "A 63-year old female was treated with the BRAF inhibitor vemurafenib for metastatic melanoma." (PMID 24289205, 2013). "Despite advances in understanding of the fundamental biology of the melanocyte and development of therapeutic agents, including the BRAF inhibitor Vemurafenib and the monoclonal antibody Ipilimumab, metastatic malignant melanoma remains an incurable disease with a poor prognosis." (PMID 22454080, 2012). "Furthermore, nivolumab plus ipilimumab was shown to be superior to dabrafenib plus trametinib as first-line therapy in patients with BRAF V600E/K-mutant metastatic melanoma, suggesting that combination immunotherapy may be a preferred option whenever feasible." (PMID 40758471, 2025). "Thus, low expression of RICTOR in metastatic melanoma is associated with a poor clinical outcome, and the gene expression signature of low RICTOR tumors indicates the activation of processes that are frequently associated with BRAF/MEKi resistance." (PMID 38755661, 2024). "In an extensive follow-up examination involving adults who had not received prior treatment for metastatic melanoma and whose tumor tissue tested positive for V600 mutations, it was noted that BRAF inhibition with vemurafenib led to an improvement of survival rates." (PMID 38541077, 2024). "Since BRAF-mutated patients treated with PLX4032 have been reported to develop resistance after 6 months, we decided to investigate the effects induced by PLX4032 chronic treatment of BRAFV600E MeOV and BRAFV600D MeTA that are human metastatic melanoma cell lines derived from two patients." (PMID 37534247, 2023). "One triple combination was approved for BRAF mutant metastatic melanoma; however, the expected synergistic effect of triple therapy could not be universally confirmed and the observed benefits with triple seem to depend on statistical considerations rather than a biological reason." (PMID 37543586, 2023). "Furthermore, dabrafenib in combination with trametinib, a MEK inhibitor, demonstrated a higher response rate and improved clinical efficacy; consequently, the FDA approved these two drugs as monotherapies as well as in combination for treating patients with BRAF-mutant metastatic melanoma." (PMID 37834222, 2023). "In addition, M-CSF contributes to metastatic melanoma resistance to BRAF-targeted therapies." (PMID 37525217, 2023). "Assessment of BRAFV600 mutant circulating cell-free tumor DNA could be a tool for therapeutic monitoring in BRAFV600 mutant metastatic melanoma patients treated with BRAF/MEK inhibitors, since a relationship has been shown between this ctDNA, durable responses, and survival outcomes." (PMID 36497340, 2022). "Probably, the comparison between treatments used on the first line in BRAF mutated metastatic melanoma may not be exhaustive by aggregating data from patients with completely different prognoses." (PMID 36046043, 2022). "Promising targeted therapies with BRAF (v-raf murine sarcoma viral oncogene homolog B1) inhibitors like vemurafenib and dabrafenib and immune checkpoint inhibitors like nivolumab and pembrolizumab have been approved for treatment of metastatic melanoma in the last decade." (PMID 34944771, 2021). "BRAFV600E can cooperate with PTEN loss to generate metastatic melanoma, while lack of p16INK4A may synergize with mutant, oncogenic, BRAF to induce metastasis." (PMID 33922182, 2021).
metastatic melanoma (continued). "This was the first indication of nivolumab in the adjuvant setting after direct comparison with ipilimumab and also one of the current first-line systemic therapy in patients with recurrent or metastatic melanoma regardless of BRAF V600 mutation status (Category 1)." (PMID 32245016, 2020). "Indeed, targeted therapies substantially improved survival in patients with advanced or metastatic melanoma from a median of 6 months obtained with chemotherapy, the standard of care before the approval of the first BRAF inhibitor, to a median of 25.9–33.6 months." (PMID 32760738, 2020). "Data published with TCGA Network, after the whole exome sequence analysis of 333 primary and/or metastatic melanoma patients, found that cutaneous melanomas could be classified into four genomic subgroups: mutant BRAF, mutant NRAS, mutant NF1, and triple-wild type." (PMID 32695793, 2020). "The implementation of immune checkpoint-inhibitors (ICIs) and BRAF (v-raf murine sarcoma viral oncogene homolog B1)/MEK (mitogen-activated protein kinase)-inhibitors (BRAFi/MEKi) over the last decade has revolutionized the standard-of-care of metastatic melanoma." (PMID 32932758, 2020). "However, few biomarkers can be used to stratify patients with regards to their response to a treatment, for example HER2 for predicting Trastuzumab efficacy for breast cancer, RAS for Cetuximab, and Panitumumab for metastatic colorectal cancer, BRAF for Vemurafenib efficacy for metastatic melanoma." (PMID 31936310, 2020). "Potent and highly selective allosteric MEK1/2 inhibitors were also developed for the treatment of oncogenic BRAF and RAS driven cancers and two of them, trametinib and cobimetinib, were approved as a single-agent therapy by the FDA for the treatment of V600E mutated metastatic melanoma." (PMID 29455659, 2018). "∙ In patients with unresectable or metastatic melanoma who no longer respond to other drugs (2014).∙ In combination with ipilimumab for the treatment of patients with BRAF V600 wild-type and BRAF V600 mutation-positive unresectable or metastatic melanoma (2015, 2016)." (PMID 28404974, 2017). "Nivolumab treatment has been shown to yield a more favorable survival benefit in previously untreated patients with metastatic melanoma not harboring a BRAF mutation as compared to dacarbazine, and it has been approved in Japan for the treatment of unresectable or metastatic melanoma." (PMID 29162045, 2017). "A combination therapy with BRAF (dabrafenib) and MEK inhibitors (trametinib) showed a significantly longer progression-free survival, a higher number of patients who were alive and progression-free at 1 year, and higher tumor regression in patients with metastatic melanoma and BRAFV600E mutation." (PMID 28918496, 2017). "A total of 83 patients were excluded including 3 patients with metastatic mucosal melanoma, 62 patients with metastatic melanoma of unknown primary, 1 patient younger than 18 at the time of treatment, and 18 with no known BRAF mutation status." (PMID 29177235, 2017). "However, it will be important to learn from lessons from therapeutic targeting of BRAF in metastatic melanoma, whereby targeting one pathway may induce resistance through upregulation of other pathways." (PMID 25785246, 2015). "Thus, the results for ipilimumab were based on all patients with metastatic melanoma, irrespective of BRAF mutation status, whereas the results for BRAF inhibitors were based on patients with BRAF mutation only." (PMID 27069772, 2015). "The selective inhibitors of BRAF codon 600 mutants, vemurafenib and dabrafenib, have been shown to improve progression-free and overall survival in metastatic melanoma patients, with either the p.V600E mutation or non-p.V600E mutations at codon 600, such as p.V600K and p.V600R." (PMID 26498038, 2015).
metastatic melanoma (continued). "Similarly, the combination of TIL with BRAF inhibitors (inducing cell apoptosis and the release of antigens which initiate T-cell activation) or BRAF/MEK inhibitors could be of interest in the treatment of metastatic melanoma." (PMID 24741578, 2014). "However, retreatment with BRAF inhibitors in BRAF-mutant metastatic melanoma patients after earlier effective therapy with vemurafenib/dabrafenib might be a treatment option but not for all patients." (PMID 25501056, 2014). "However, no data have yet defined which the best sequence is and more research is needed to identify predictors of response in patients with metastatic melanoma to help guide whether a BRAF inhibitor or ipilimumab should be used first in sequential therapy." (PMID 23497384, 2013). "Considering that metastatic melanomas are frequently characterized by BRAF V600E heterozygous mutation, we assessed its role on c-FOS stability by transiently transfecting BRAF V600E in the early primary Me1007 cell line, endogenously expressing wild-type BRAF." (PMID 23400877, 2013). "Current therapies including drugs targeting BRAF and MEK significantly improve the prognosis of metastatic melanoma patients, yet innate or acquired resistance challenges long-term responses." (PMID 41872166, 2026). "Combination BRAF/MEK inhibitor therapy has improved the progression‐free and overall survival of patients with BRAFV600 mutant metastatic melanoma relative to either dacarbazine or single agent BRAFi therapy." (PMID 41514118, 2026). "Of note, a recruiting phase II clinical trial (NCT04633902) will evaluate the use of pembrolizumab with Olaparib and its clinical efficacy in treating metastatic melanoma that has been refractory to ICI and BRAF inhibitors treatment." (PMID 40842586, 2025). "The clinical effect of these shared resistance mechanisms was demonstrated in the DREAMSeq and SECOMBIT trials assessing the sequencing of BRAF/ MEKi and ICI in metastatic melanoma." (PMID 40362630, 2025). "Presently, targeted therapies for the treatment of metastatic melanoma are stratified based on tumor stage (e.g., stage IV), mutant genotype (e.g., MEK/BRAF inhibitors), or the expression levels of key biomarkers such as PD-L1." (PMID 40722520, 2025). "Another study in Frontiers evaluated the efficacy of triplet combination therapy with BRAF inhibitors, MEK inhibitors, and PD-1/PD-L1 inhibitors in patients with metastatic melanoma." (PMID 40004731, 2025). "Combined with BRAF/MEK-directed therapy, these treatments have dramatically improved the prognosis for patients with metastatic melanoma." (PMID 40331942, 2025). "The introduction of BRAF and MEK inhibitors has dramatically improved the survival of metastatic melanoma patients." (PMID 37953496, 2024). "Multiple regimens using combination BRAF and MEK inhibition have been approved in the interim, and they remain important options for BRAF-mutant metastatic melanoma." (PMID 39542696, 2024). "While BRAF/MEK and PI3K/AKT pathway inhibitors represent an intriguing therapeutic option for patients with metastatic melanoma, the success of these therapeutics is reduced by the development of acquired resistance via MSC-dependent mechanisms." (PMID 38275910, 2024). "A correlation between clinical outcome and antitumor immunity has been demonstrated in both BRAF + MEK inhibitor-treated and anti-PD-1-treated metastatic melanoma patients." (PMID 39272837, 2024). "A recent multicenter study evaluated the occurrence of hyperprogression disease in metastatic melanoma patients treated with ICI, BRAF/MEK inhibitors or chemotherapy." (PMID 39148899, 2024). "Several FDA-approved BRAF or MEK inhibitors (vemurafenib, dabrafenib, and trametinib) have shown promise in improving PFS, RR, and OS for patients with metastatic melanoma." (PMID 37205993, 2023).